CASP9 (caspase 9)
Diseases named in the same sentence as CASP9 in open-access papers (continued):
Sharing a sentence is not in itself a finding about the gene and the disease.
Sepsis (27 papers, 2011 to 2025). Sepsis is defined as life-threatening organ dysfunction caused by a dysregulated host response to infection. "Our study found that cardiomyocyte apoptosis increased in CLP-induced murine sepsis, and pretreatment with rutin significantly attenuated increases in Bax levels and associated activation of caspase-9 and reduced cardiomyocyte apoptosis in SIC." (PMID 35492613, 2022). "Secondly, we showed that survivin is correlated with IL-8 and caspase-9, which is independently associated with sepsis, achieving the best, among others, sepsis discrimination and outcome predictive-ability." (PMID 33441606, 2021). "In a logistic regression model, only caspase-9 was independently associated with sepsis among critically ill patients (Exp(B) = 1.2, 95%CI = 1.09–1.4, p < 0.04)." (PMID 33441606, 2021). "In addition, we demonstrated that the oxidant-antioxidant imbalance is an early-onset sepsis discriminator associated with mortality and accompanied by augmentation of the intrinsic mitochondrial apoptotic pathway caspase-9 and the effector of intrinsic and extrinsic apoptotic pathways caspase-3." (PMID 35204114, 2022). "In vivo studies have proven the cardioprotective role of anti-apoptosis during sepsis and highlighted the engagement of Bax, Bcl-2, Bcl-xl, Caspase 3, and Caspase 9 in sepsis-induced cardiomyocyte apoptosis." (PMID 37650558, 2023). "LPS plays a crucial role in the constellation of sepsis, resulting in apoptotic damage to organelles, including mitochondria, that can modulate the intrinsic pathway via mediators activating caspase-9." (PMID 35794865, 2022). "In this study, we showed that caspase-9 and caspase-3 are simultaneously induced in early-onset sepsis." (PMID 35204114, 2022). "For discriminating sepsis, caspase-9 achieved the best receiver operating characteristic curve (AUROC) of 0.95." (PMID 33441606, 2021). "Then, PQQ treatment rescued the reduction of Bcl-2 expression and elevation of Bax, Cleaved caspase-3 and Cleaved caspase-9 expression, alleviating sepsis-induced cell apoptosis of liver tissues." (PMID 34227919, 2021). "It was observed that expressions of Bax, Cleaved caspase-3 and Cleaved caspase-9 were enhanced and Bcl-2 expression was decreased after the occurrence of sepsis." (PMID 34227919, 2021). "The number of naïve and memory CD8+ T cells is reduced by sepsis-induced apoptosis, as indicated by increased caspase 9, Bim, and Bid expression and decreased Bcl-2 expression in CD8+ T cells isolated from patients with sepsis." (PMID 33532141, 2021). "Various pathways seem to be involved in the lymphocyte apoptosis in case of sepsis: an extrinsic pathway, mediated by the caspase-8, and an intrinsic pathway, mediated by the caspase-9." (PMID 28303547, 2017). "The sepsis-induced increase in the activated capase-3 and caspase-9 levels returned to the control levels after rhHsp72 administration (comparison between empty and shaded columns)." (PMID 26221596, 2015). "Besides this, local thymic caspase-9 inhibition decreased lymphocyte apoptosis during polymicrobial sepsis in septic animal models." (PMID 33441606, 2021). "Additionally, MRS treatment downregulated the expression of cytochrome c, caspase-3 and caspase-9, reduced apoptosis and alleviated sepsis damage." (PMID 30779706, 2019). "Therefore we used co-immunoprecipitation and immunoblotting to examine the effects of AdHSP on the sepsis-induced formation of complexes containing pro-caspase 3, caspase 8 and caspase 9, as well as Apaf-1." (PMID 22132083, 2011).
Sepsis (continued). "Our study also found an increased expression of the caspase-3, and caspase-9 in the PFC and changes in cardiolipin in hippocampus of sepsis survivors’ animals." (PMID 35606817, 2022). "We examined the protein levels of caspase-3, caspase-9, and cardiolipin in the PFC and hippocampus 24 h and 10 days after sepsis." (PMID 35606817, 2022). "The apoptosis during immune paralysis in sepsis is believed to be induced by caspase signals, namely death receptor induced caspase 8 (CASP8) or mitochondrial induced caspase 9 (CASP9)." (PMID 28056766, 2017). "The Bcl-2/Bax ratio, cleaved caspase-3, caspase-9, and PARP protein expressions in the liver tissues were upregulated during sepsis and normalized after rhHsp72 treatment." (PMID 26221596, 2015). "In addition, DEX dramatically prevented sepsis-induced pulmonary cell apoptosis in mice, as reflected by decreases in the number of TUNEL-positive cells, the protein expression of cleaved caspase-9 and cleaved caspase 3 and the Bax/Bcl-2 ratio." (PMID 31927655, 2020). "The expression of the proteins Bax, Cleaved-Caspase 3, Cleaved-Caspase 9, Cytochrome C, and Cleaved-PARP were significantly increased, whereas the expression of Bcl-2 was significantly decreased in the myocardium of rat with sepsis as compared with the Sham group at the same point of time." (PMID 37219401, 2023). "No change in the levels of caspase-3 and caspase-9 were found in the hippocampus after sepsis." (PMID 35606817, 2022). "Furthermore, we found that the protein expression levels of Bax, Caspase-3, and Caspase-9 were significantly lower, and the protein expression levels of Bcl-2 were significantly higher in Group B. These results indicate that PTX3 inhibits the apoptotic ability of cardiomyocytes in sepsis." (PMID 38784395, 2024).
multiple myeloma (26 papers, 2008 to 2025). "Bortezomib requires caspase-8 and caspase-9, whereas marizomib induces the apoptotic effect mainly through caspase-8 signaling that allows it to overcome the resistance of myeloma cells conferred by Bcl-2 mutations." (PMID 26579531, 2015). "We found that Bik-induced cell death in myeloma cells is associated with caspase-9 and caspase-3 activation suggesting that Bik promotes cell apoptosis through a mitochondrial–associated caspase pathway in myeloma cells." (PMID 21063407, 2010). "However, the overactivation of caspase-8 has been found in drug-resistant myeloma cells and, in some cancers, caspases such as caspase-8 and caspase-9 are linked to increased tumorigenesis, survival and invasion." (PMID 37686623, 2023). "In our study, we found that MYXV treatment increased caspase-9 expression in myeloma cells of both newly diagnosed and recurrent MM patients." (PMID 38251379, 2024). "Myeloma cell death was associated with dual PI and Annexin-V positivity and increased expression of apoptotic genes, including CASP1, CASP8, CASP9, BAX, BID, and FASL." (PMID 36992311, 2023). "Knockdown of SNHG16 in multiple myeloma cells suppressed cell proliferation, induced cell arrest and promoted the apoptosis via inducing cleaved-Caspase-3, cleaved-Caspase-9, Foxa3a and Bax expression, while inhibiting CCND1, Bcl-2, Cyclin D1, PI3K and p-AKT." (PMID 35740344, 2022). "Bor is a widely used proteasome inhibitor known to induce apoptosis through caspase-8 and caspase-9 signaling which further leads to caspase-3 activation in multiple myeloma cells." (PMID 32653014, 2020). "The SK2 inhibitor ABC294640 has been shown to induce apoptotic death, as demonstrated by annexin V staining, poly (ADP-ribose) polymerase (PARP), and caspase 9 activation of both primary myeloma cells and myeloma cell lines." (PMID 31801274, 2019). "Decursin enhanced caspase-9-mediated apoptosis in doxorubicin-treated multiple myeloma cells, via the mTOR and STAT3 pathways and other reports showed that decursin increased caspase-8-mediated apoptosis by increasing TRAIL sensitivity." (PMID 30155480, 2018). "Chloramphenicol increased levels of cytochrome c, cleaved caspase-9 and cleaved caspase-3, suggesting that myeloma cell apoptosis occurs through the mitochondria-mediated apoptosis pathway." (PMID 27437770, 2016). "In an in vitro study, it has been demonstrated that oprozomib inhibits growth and migration of myeloma cell lines and induces apoptosis through the activation of caspase-8, caspase-9 and caspase-3 and poly(ADP) ribose polymerase (PARP)." (PMID 26579531, 2015). "The overexpression of Bcl-2 is demonstrated to protect the myeloma cells by bortezomib and to some extent by marizomib too, due to its caspase-9 activation." (PMID 26579531, 2015). "In multiple myeloma cells, bortezomib has been shown to activate both the intrinsic apoptotic pathway, involving mitochondrial cytochrome c release and caspase-9, as well as the extrinsic, Fas/caspase-8-dependent apoptotic pathway." (PMID 23226303, 2012). "Oleocanthal has already been shown to induce cytotoxicity and apoptosis in vitro in human acute promyelocytic leukemia HL-60 cells, myeloma ARH-77 cells and murine myeloma MOPC-31C, to cause G1 arrest in ARH-77 cells and to promote their apoptosis by the activation of caspase-9/-3." (PMID 35127522, 2021). "Indeed, it has been shown to confer protection from dexamethasone-induced apoptosis by activating PI3K/Akt signaling and inactivating caspase-9, thereby inhibiting apoptosis in multiple myeloma cells." (PMID 29930760, 2018). "Furthermore, cleavage of caspase-9 was observed in three multiple myeloma cells by the combination of decursin and doxorubicin in a time-dependent manner in U266 cells." (PMID 23818927, 2013).
multiple myeloma (continued). "As caspase-9 is activated through the intrinsic pathway, initiated by the disruption of the mitochondrial membrane and cytochrome c release, we evaluated mitochondrial membrane function and release of cytochrome c in Aplidin-treated 5T33MMvt myeloma cells." (PMID 18521088, 2008). "Treatment-induced protein expression of the phenotypic/functional markers of myeloma (p65/NFκB, IRF4, and cMyc) and markers of apoptosis (including Cleaved Caspase-3, Cleaved Caspase-9, etc.)was confirmed using immunoblotting analysis in HMCLs." (PMID 35264575, 2022). "Upon anti-β2m treatment, MHC-I was internalized and caspase-9, -3, -7 and poly (ADP-ribose) polymerase (PARP) were activated in myeloma cells." (PMID 33384693, 2020). "Exposure of human multiple myeloma cells to Tetrac typically results in caspase-9 and caspase-3 activation but not activation of the DNA-cleaving apoptosis inducing factor (AIF)." (PMID 36412991, 2022). "In mice, anti-β2m injections reduced tumor volumes and improved survival, whereas no other tissues were damaged, and pJNK, cleavage of caspase-9 and caspase-3 and myeloma apoptosis were induced." (PMID 33384693, 2020). "DHAP-induced apoptosis in multiple myeloma cells was detected by Annexin V staining and TUNEL staining (DNA fragmentation), and further confirmed by the activation of caspase-3, caspase-8, and caspase-9, and PARP cleavage." (PMID 28696369, 2017). "Furthermore, the combination treatment enhanced the activation of caspase-9 and -3, the cleavage of PARP, and the sub G1 population compared to either drug alone in three multiple myeloma cells." (PMID 23818927, 2013). "Moreover, SMAC has been shown to lead to caspase-9 activation without the concurrent release of cyt c in human multiple myeloma cells." (PMID 30670698, 2019).
liver cancer (25 papers, 2011 to 2025). An epithelial or non-epithelial malignant neoplasm that arises from the liver. "To further understand the mechanism by which Ad.SPDD-HCCS1 caused apoptosis of liver cancer cells, we evaluated the key apoptosis-related proteins caspase-3, caspase-8 and caspase-9." (PMID 22040050, 2011). "Meanwhile, it promotes the activation of Caspase 9, the direct target protein downstream of Akt, further activates the downstream Caspase 3 protein, and finally inhibits the proliferation of liver cancer cells and causes apoptosis of liver cancer cells." (PMID 36110518, 2022). "Meanwhile, Annexin V-FITC/PI staining and western blot analysis of cleaved caspase 9 and cleaved caspase 3 demonstrated that SS-b2 induced apoptosis of HepG2 liver cancer cells." (PMID 39544485, 2024). "The natural compound curcumin, in combination with fluorouracil, induces apoptosis via the downregulation of BCL2 and the upregulation of cleaved caspase-9 and caspase-3 in liver cancer cells." (PMID 39765861, 2024). "Treatment with SS-b2 (40 or 80 mg/L) for 24 h caused a steady decrease in the protein expression of Bcl-2 in HepG2 liver cancer cells, whereas the expression of Bax, Cyt-c, cleaved caspase 9 and cleaved caspase 3 dramatically increased." (PMID 39544485, 2024). "In comparison with the blank group, LFE regulated the mRNA expression levels of PTEN, PI3K, AKT, PDCD4, VEGFA, Caspase 9, Caspase 3, Bcl-2, Bax and Bad in liver cancer cells to different degrees." (PMID 36110518, 2022). "Compared with the blank group, LFE regulated the proteins expression levels of PTEN, PI3K, p-PI3K, Akt, p-Akt, VEGFA and Caspase 9 in liver cancer cells to different degrees." (PMID 36110518, 2022). "After 0.178 and 0.185 μmol/L propofol acted on liver cancer cells 24, Western-Blot experiment found that compared with the control group, propofol significantly reduced the expression of the apoptotic protein ProCaspase-9 protein and increased the protein level of Cleaved Caspase-9." (PMID 34323647, 2021). "Akt-knockout liver cancer cells showed lower p-Bad expression and higher Bad expression, which reduces Bcl-xL expression and promotes down-stream signals, such as cytochrome c, Apaf-1, caspase-9 and caspase-3 expression, and it subsequently contributes to apoptosis in cancer cells." (PMID 29502513, 2017). "Thus, we speculate that TM4SF1 upregulation inhibits apoptosis and induces abnormal proliferation of liver cancer cells by downregulating caspase-3 and caspase-9, and that this leads to the onset and progression of liver cancer." (PMID 27153056, 2016). "(ii) Ceramide production: In PA-mediated HepG2 (a human liver cancer cell line) apoptosis, PA-activated dihydroceramide desaturase 1 (DES1) → ceramide → caspase 9 → caspase 3 signaling." (PMID 37174432, 2023). "From 12 h post transfection onwards, SARM overexpression significantly elevated the activities of caspase-9 in HCC cells (P<0.01), suggesting that SARM acts via intrinsic apoptosis in liver cancer." (PMID 27551463, 2015). "In order to reaffirm the involvement of caspases in Far-C-instigated cytotoxicity in HepG2 cells, MTT assay was carried out in human liver cancer HepG2 cells pretreated with Z-LEHD-FMK and ZDEVD-FMK (50 μM each for 2 h) which are specific inhibitors of caspase-9 and caspase-3, respectively." (PMID 36145291, 2022). "Moreover, protein expression of cleaved-PARP, cleaved caspase 3, and cleaved caspase 9 in Huh7 were increased by knockdown of PITX2, suggesting the anti-apoptotic effect of PITX2 on liver cancer cells." (PMID 35071766, 2021). "However, in liver cancer cell lines, glutamine deprivation did not induce caspase-9 or -8 activation, but rather stimulated caspase-2 activity." (PMID 27419628, 2016).
liver cancer (continued). "Thus, we speculate that in the early pathogenesis of liver cancer, TM4SF1 has a central role in the inhibition of apoptosis and autophagy that is mediated through its effects on caspase-3 and caspase-9." (PMID 27153056, 2016).
bladder cancer (23 papers, 2007 to 2025). "Activation of both caspase-9 and caspase-8 was observed in the testis tumor cells 48 h after cisplatin treatment, the bladder cancer cell lines responded later and to a lesser extent." (PMID 37891379, 2024). "Our results showed that treatment of bladder cancer cells 253J and T-24 led to the increase of cleaved caspase-9 and caspase-3." (PMID 26931119, 2016). "Our results showed that the knockdown of AATBC by RNAi technology led to the apoptosis of bladder cancer cells via the intrinsic apoptosis signal, as shown by the activation of caspase-9 and caspase-3." (PMID 25473900, 2015). "In this study, JS-K promoted ROS levels, increased cytotoxicity and caspase-3/7 activity, and activated caspase-9 protein in bladder cancer cells in a concentration-dependent manner; these effects, in turn, induced cellular apoptosis." (PMID 26458509, 2015). "Cleavages of caspase-9 and -3 increased time- and dose- dependently in bladder cancer cells treated with Tan-IIA." (PMID 25192287, 2014). "Evodiamine activated caspase-9 and caspase-8 in bladder cancer cells 253J and T24, indicating that both the intrinsic and extrinsic apoptotic pathways were involved in the evodiamine-induced apoptosis." (PMID 24566141, 2014). "Activation of caspase 9 pathway in bladder cancer cells is very likely triggered by down regulation of Bcl-2 family genes and inhibitors of apoptotic proteins (IAP)." (PMID 18939995, 2008). "CASPASE 9 was upregulated in a bladder carcinoma cell line exposed to 50 μg/mL concentration of Brazilian red propolis, but it downregulated when 100 μg/mL was used, suggesting that propolis could activate independent caspase apoptosis pathways." (PMID 34083947, 2021). "Our findings showed that the activation of caspase-3 and caspase-9 was induced by the knockdown of linc00511, indicating that the linc00511 might be a therapeutic target for bladder cancer treatment once again." (PMID 30042171, 2018). "Besides, our results demonstrated that the mitochondria-dependent pathway was involved in Tan-IIA-induced apoptosis in these human bladder cancer cells: Tan-IIA induced caspase-9 and caspase-3 cleavages in a time- and dose-dependent manner." (PMID 25192287, 2014). "Moreover, higher dosages of CuE (0.5–1 μM) induced the up-regulation of Fas/CD95, truncated BID (t-BID), AIF, and sequential activation of caspase-8, caspase-9, and caspase-3 in T24 bladder cancer cells." (PMID 25072848, 2014). "The molecular mechanism that BJOE induces apoptosis of T24 bladder cancer cells may be the activation of caspase apoptotic pathway by upregulation of the expression of caspase-3 and caspase-9 proteins and inhibition of the expression of NF-κB and cyclo-oxyge-nase-2 (COX-2) proteins." (PMID 29649989, 2018). "This study identified five prognostic biomarker genes related to mitochondrial function and programmed cell death in bladder cancer (POLB, FASN, CASP9, VDAC2, and RHOT2) and preliminarily constructed a prognostic model based on these genes." (PMID 41427247, 2025). "The Univariate Cox regression analysis revealed that eight PRGs (PRKACA, GSDMB, CASP9, GSDMD, CASP6, CASP8, AIM2, and CASP1) were significantly correlated with the prognosis in bladder cancer." (PMID 36120583, 2022). "Increased activity of caspase-9 and caspase-3/7 and increased levels of cleaved PARP were detected in JS-K-treated bladder cancer cells compared with the controls." (PMID 26458509, 2015). "Western blot analysis demonstrates that BIX-01294 (0, 5, 10 μmol/l) significantly activated CASP8, CASP9, CASP3 and cleaved the substrate of CASP3, PARP1 in bladder cancer cells treated for 24 hours." (PMID 25685062, 2015). "In this study, we confirmed that JS-K increases levels of cleaved caspase-9 and PARP proteins in bladder cancer cells but decreases the level of Bcl-2 protein." (PMID 26458509, 2015).